DHX36 (DEAH-box helicase 36)
Description:
Multifunctional ATP-dependent helicase that unwinds G-quadruplex (G4) structures. Plays a role in many biological processes such as genomic integrity, gene expression regulations and as a sensor to initiate antiviral responses. G4 structures correspond to helical structures containing guanine tetrads (By similarity). Binds with high affinity to and unwinds G4 structures that are formed in nucleic acids (G4-DNA and G4-RNA). Plays a role in genomic integrity. Converts the G4-RNA structure present in telomerase RNA template component (TREC) into a double-stranded RNA to promote P1 helix formation that acts as a template boundary ensuring accurate reverse transcription. Plays a role in transcriptional regulation. Resolves G4-DNA structures in promoters of genes, such as YY1, KIT/c-kit and ALPL and positively regulates their expression. Plays a role in post-transcriptional regulation. Binds to the precursor-microRNA-134 (pre-miR-134) terminal loop and regulates its transport into the synapto-dendritic compartment (By similarity). Involved in the pre-miR-134-dependent inhibition of target gene expression and the control of dendritic spine size (By similarity). Plays a role in the regulation of cytoplasmic mRNA translation and mRNA stability. Binds to both G4-RNA structures and alternative non-quadruplex-forming sequence within the 3'-UTR of the PITX1 mRNA regulating negatively PITX1 protein expression. Binds to both G4-RNA structure in the 5'-UTR and AU-rich elements (AREs) localized in the 3'-UTR of NKX2-5 mRNA to either stimulate protein translation or induce mRNA decay in an ELAVL1-dependent manner, respectively. Also binds to ARE sequences present in several mRNAs mediating exosome-mediated 3'-5' mRNA degradation. Involved in cytoplasmic urokinase-type plasminogen activator (uPA) mRNA decay. Component of a multi-helicase-TICAM1 complex that acts as a cytoplasmic sensor of viral double-stranded RNA (dsRNA) and plays a role in the activation of a cascade of antiviral responses including the induction of pro-inflammatory cytokines via the adapter molecule TICAM1 (By similarity). Required for early embryonic development and hematopoiesis. Involved in the regulation of cardioblast differentiation and proliferation during heart development. Involved in spermatogonia differentiation. May play a role in ossification (By similarity).
Synonyms: G4R1; DDX36; KIAA1488; MLEL1; RHAU
Tractability: PROTAC: ubiquitination databases record sites on it; its protein half-life has been measured.
Target class: Enzyme
Gene: Protein-coding gene on chromosome 3 (154,272,546 to 154,324,487, reverse strand). Ensembl gene ENSG00000174953.
Subcellular location: Nucleus; Cytoplasm; Cytoplasm, cytosol; Cytoplasm, Stress granule; Nucleus speckle; Chromosome, telomere; Mitochondrion; Perikaryon; Cell projection, dendrite; Cell projection, axon; Nucleus (Isoform 1); Nucleus (Isoform 2)
Subcellular location (Human Protein Atlas): Cytosol; Nucleoplasm
Pathways (Reactome):
Immune System: DEx/H-box helicases activate type I IFN and inflammatory cytokines production
Gene Ontology:
Molecular function: ATP hydrolysis activity; ATP-dependent activity, acting on DNA; DNA helicase activity; double-stranded RNA binding; G-quadruplex DNA binding; G-quadruplex RNA binding; G-quadruplex unwinding activity; magnesium ion binding; mRNA 3'-UTR AU-rich region binding; mRNA 3'-UTR binding; mRNA 5'-UTR binding; protein binding; RNA binding; RNA helicase activity; RNA polymerase II cis-regulatory region sequence-specific DNA binding; single-stranded DNA binding; telomerase RNA binding; ATP binding; histone deacetylase binding; pre-miRNA binding; transcription cis-regulatory region binding; nucleic acid binding
Biological process: 3'-UTR-mediated mRNA destabilization; cellular response to arsenite ion; cellular response to heat; cellular response to UV; negative regulation of translation; positive regulation of cytoplasmic translation; positive regulation of interferon-alpha production; positive regulation of mRNA 3'-end processing; positive regulation of nuclear-transcribed mRNA catabolic process, deadenylation-dependent decay; positive regulation of telomere maintenance; positive regulation of telomere maintenance via telomere lengthening; positive regulation of transcription initiation by RNA polymerase II; regulation of mRNA stability; regulation of transcription by RNA polymerase III; telomerase RNA stabilization; ossification; positive regulation of canonical NF-kappaB signal transduction; positive regulation of cardioblast differentiation; positive regulation of dendritic spine morphogenesis; positive regulation of gene expression; positive regulation of hematopoietic progenitor cell differentiation; positive regulation of intracellular mRNA localization; positive regulation of transcription by RNA polymerase II; regulation of embryonic development; spermatogenesis; and 2 more
Cellular component: chromosome, telomeric region; cytoplasm; cytoplasmic stress granule; cytosol; extracellular exosome; nuclear speck; nucleoplasm; nucleus; axon; dendrite; mitochondrion; perikaryon
Genetic constraint (gnomAD): Loss-of-function variants: 29 observed, 98.55 expected, observed/expected ratio (o/e) 0.29, 90% interval 0.22 to 0.4. The upper end of that interval is the gene's LOEUF score, 0.4, which puts it in group 1 of 6, group 1 being the genes least tolerant of losing a copy. Missense variants: 795 observed, 995.05 expected, observed/expected ratio (o/e) 0.8, 90% interval 0.75 to 0.85. Synonymous variants: 342 observed, 336.45 expected, observed/expected ratio (o/e) 1.02, 90% interval 0.93 to 1.11.
Homologues: Orthologues: chimpanzee DHX36 (99% identical), macaque DHX36 (99% identical), pig DHX36 (93% identical), mouse Dhx36 (92% identical), rat Dhx36 (91% identical), dog DHX36 (91% identical), rabbit DHX36 (90% identical), guinea pig DHX36 (84% identical), tropical clawed frog dhx36 (70% identical), zebrafish dhx36 (65% identical), Drosophila melanogaster Rhau (35% identical). Paralogues in human: DHX57 (41% identical), DHX29 (35% identical), YTHDC2 (33% identical), DHX9 (32% identical), DHX30 (29% identical), DHX34 (25% identical), TDRD9 (24% identical), DHX8 (23% identical), DHX15 (22% identical), DHX16 (22% identical), DHX37 (22% identical), DHX38 (22% identical), and 6 more.
Diseases named in the same sentence as DHX36 in open-access papers:
DHX36 is named in the same sentence as 32 diseases in open-access papers, as found by Europe PMC text mining. Sharing a sentence is not in itself a finding about the gene and the disease. The quoted sentences say what the papers report.
viral infection (9 papers, 2014 to 2024). "DHX36 RNA helicases have been reported to be involved in RLR-mediated type I IFN production after viral infection, and induce an innate immune response." (PMID 38715092, 2024). "In this minireview, we provide a brief overview of G4/DHX36 interaction and a brief summary of recent discoveries in the field with emphasis given to DHX36’s role in cancer, telomere maintenance, and viral infection." (PMID 34862880, 2021). "During viral infections, the helicase activity of DHX36 induces PKR, which results in SG formation and leads to initiation of immune responses." (PMID 34862880, 2021). "In this report, we describe the involvement of DHX36 in sensing viral infection and subsequent activation of RIG-I." (PMID 24651521, 2014). "Under the condition of viral infection, DHX36:RIG-I complex recognizes dsRNA and interacts with PKR." (PMID 24651521, 2014). "In cytoplasm, DHX36 plays important roles in sensing poly I:C and viral infection." (PMID 29123520, 2017). "DDX3, DHX29, DHX36, and DDX60 RNA helicases have been reported to be involved in RLR-mediated type I IFN production after viral infection." (PMID 27252702, 2016). "Intriguingly, virus infection induced hyperphosphorylation of PKR and this phosphorylation was markedly attenuated by DHX36 deletion." (PMID 24651521, 2014). "Because our data suggest that DHX36 is required for avSG formation, we further examined the effect of DHX36 deletion on PKR phosphorylation induced by viral infection." (PMID 24651521, 2014). "Viral infection induces the formation of avSGs, including conventional SG markers, RIG-I, MDA5, LGP2, PKR, OAS, RNase L, DHX36, TRIM25, PUM1 and PUM2, some of which are critical in sensing non-self viral RNA and triggering antiviral signaling." (PMID 25340845, 2014). "In this report, we examined the role of DHX36 in the host innate immune response by virus infection and non-self RNA ligand transfection in fibroblast cells." (PMID 24651521, 2014). "In contrast to the viral infections examined, DHX36 did not affect IFN-ß induction by 5′ppp-cbRNA, even though this stimulus activates RIG-I." (PMID 24651521, 2014). "DHX36 interacted with RIG-I regardless of virus infection in its CTD-dependent manner." (PMID 24651521, 2014). "DHX36 was found to physically interact with RIG-I regardless of virus infection." (PMID 24651521, 2014).
colon cancer (6 papers, 2021 to 2025). "GSEC has recently been shown to directly interact with and inhibit the RNA helicase DHX36 (DEAH box polypeptide 36) in a colon cancer cell line." (PMID 33544756, 2021). "GSEC is a G-quadruplex-containing lncRNA that can bind to DHX36, thus inhibiting the unwinding activity of G-quadruplexes to promote colon cancer cell metastasis." (PMID 34778084, 2021). "Matsumura and colleagues reported that GSEC could inhibit the function of DHX36 to promote colon cancer cell migration." (PMID 36227151, 2022). "The knockdown of GSEC was reported to reduce motility activity in colon cancer cells, and in addition, GSEC could bind DHX36 to reduce its activity to promote colon cancer development." (PMID 35482720, 2022). "Overexpression of DHX36 inhibits the motility of the colon cancer cell line DLD-1." (PMID 34778084, 2021). "Also, an RNA gene named G-Quadruplex Forming Sequence Containing LncRNA (GSEC) can bind to DHX36 via its G4 sequence, leading to the antagonisation of DHX36 and enhanced migration of colon cancer cells." (PMID 33987090, 2021).
amyotrophic lateral sclerosis (3 papers, 2022 to 2024). Amyotrophic lateral sclerosis (ALS) is a neurodegenerative disease characterized by progressive muscular paralysis reflecting degeneration of motor neurons in the primary motor cortex, corticospinal tracts, brainstem and spinal cord. "G4-PROTAC is designed for specific degradation of a G4-binding protein (RHAU/DHX36) which has been reported to be highly expressed in tissues of C9orf72-linked amyotrophic lateral sclerosis (ALS) patients and thus represents an important therapeutic target." (PMID 35625576, 2022).
colorectal cancer (2 papers, 2021 to 2025). A primary or metastatic malignant neoplasm that affects the colon or rectum. "In colorectal cancer, GSEC influences tumor migration by inhibiting DHX36 function through G-quadruplex structures." (PMID 38684626, 2025).
glioblastoma (2 papers, 2020 to 2022). The most malignant astrocytic tumor (WHO grade IV). "A similar ‘bind-unfold-lock’ mechanism was proposed for USP1 translational regulation by hnRNP H/F and DHX36 in glioblastoma or for the CNBP-targeted mRNAs." (PMID 36107769, 2022).
glioma (2 papers, 2020 to 2024). A benign or malignant brain and spinal cord tumor that arises from glial cells (astrocytes, oligodendrocytes, ependymal cells). "Suppress the cell proliferation in glioma cells by forming RO-AIMs/ helicase DHX36/ c-Myc complex that inhibits c-Myc." (PMID 38786726, 2024). "Based on in silico analysis, it has been postulated that RO-AIMs exert their effect by interacting with the DEAH-Box helicase 36 (DHX36) and c-Myc in a ternary complex, halting glioma cell proliferation." (PMID 38786726, 2024). "Finally, to investigate the potential clinical importance of our findings, we analyzed the expression of hnRNP H/F, DHX36 and USP1 in human glioma patient tissues." (PMID 32461552, 2020).
melanoma (2 papers, 2020 to 2025). A malignant, usually aggressive tumor composed of atypical, neoplastic melanocytes. "Other tested DNA sensors (Cgas, Sting, Ddx41, Dhx9, Dhx36, Lrrfip1, Mre11, and additionally Aim2, which is absent in melanoma cells) were expressed in macrophages but were not significantly upregulated after irradiation." (PMID 33202881, 2020).
non-small cell lung carcinoma (2 papers, 2021 to 2022). A group of at least three distinct histological types of lung cancer, including non-small cell squamous cell carcinoma, adenocarcinoma, and large cell carcinoma. "DHX9 promotes migration of lung adenocarcinoma cells, whereas DHX36 knockdown increases migration and proliferation and reduces chemotherapeutic responses in non-small-cell lung carcinoma (NSCLC)." (PMID 36012592, 2022). "In this study, by bioinformatic analysis of public datasets (TCGA and GEO), we find DHX36 is an independent prognosis indicator in non-small-cell lung carcinoma (NSCLC) with subtype dependence." (PMID 33987090, 2021). "In this study, we intended to evaluate the differential expression and prognostic value of DHX36 in patients with non-small-cell lung carcinoma (NSCLC)." (PMID 33987090, 2021).
testicular cancer (2 papers, 2023 to 2025). A primary or metastatic malignant neoplasm that affects the testis. "A recent report suggested that piR-36249 regulates testicular cancer progression by engaging with DHX36 to regulate OAS2." (PMID 37662498, 2023).
age (1 paper, 2024). A temporal measurement of the time period elapsed since an identifiable point in the life cycle of an organism. "Site-specific resolution of G4-DNA by dCas9-mediated deposition of the helicase DHX36 impairs fear extinction memory, possibly implicating DHX36 in age-associated cognitive impairment." (PMID 39444378, 2024).
atherosclerosis (1 paper, 2026). A disease characterized by the build-up of fatty material and calcium deposition in the arterial wall resulting in partial or complete occlusion of the arterial lumen. "The association of DHX36 with the spliceosome suggests that it may influence gene expression profiles relevant to atherosclerosis, potentially affecting the stability and function of mRNAs involved in inflammatory responses and lipid metabolism." (PMID 41614904, 2026). "This leads us to hypothesize that CD8+ T cells may further inhibit the progression of atherosclerosis through mechanisms involving DHX36 or GPR68." (PMID 41614904, 2026). "The enrichment analysis identified several critical pathways associated with the biomarkers DHX36 and GPR68, which may play pivotal roles in the pathogenesis of atherosclerosis." (PMID 41614904, 2026). "The negative correlation with these biomarkers suggests that higher levels of DHX36 and GPR68 may be associated with reduced monocyte activity or recruitment, which could impact the inflammatory processes underlying atherosclerosis." (PMID 41614904, 2026). "Collectively, these pathways underscore the multifaceted roles of DHX36 and GPR68 in atherosclerosis and warrant further investigation into their potential as therapeutic targets." (PMID 41614904, 2026).
germ cell tumor (1 paper, 2023). A benign or malignant, gonadal or extragonadal neoplasm that originates from germ cells. "Interestingly RNA helicases DHX36 and DDX41 were inhibited in DSD-GCT (labeled green), potentially implying the redundant role of RNA regulation in innate immune response induction in patients with germ cell tumor." (PMID 37217472, 2023).
leukemia (1 paper, 2021). A malignant (clonal) hematologic disorder, involving hematopoietic stem cells and characterized by the presence of primitive or atypical myeloid or lymphoid cells in the bone marrow and the blood. "DHX36 has been implicated in leukemia through interaction with apoptosis and caspase activation inhibitor, AVEN, to increase translation of leukemogenic transcriptional regulators MLL1 and MLL4, and subsequent proliferation of leukemic cells." (PMID 33544756, 2021).
lung carcinoma (1 paper, 2021). "KM plotting analysis indicated high DHX36 gene expression was associated with poor overall survival of lung cancer patients (HR=1.32, logrank p=0.0025, n=1144)." (PMID 33987090, 2021). "The DHX36 knockdown accelerates migration and aggregation of the S-phase subpopulation in lung cancer cells." (PMID 33987090, 2021). "The role of DHX36 in lung cancer cells was also investigated using stable lung cancer cell models following DHX36 knockdown." (PMID 33987090, 2021). "We verified the differential gene expression of DHX36 in lung cancer using our in-house cohort by qRT-PCR." (PMID 33987090, 2021). "The reduction of DHX36 level de-sensitises the proliferation response of lung cancer cells to chemotherapeutic drugs such as paclitaxel with cell dependence." (PMID 33987090, 2021). "However, our differential gene expression analysis indicates that in both LUSC and LUAD subtypes, the levels of DHX36 gene expression in lung cancer are higher than in normal tissues." (PMID 33987090, 2021). "The possible discovery of DHX36 targeting may be translated to the treatment of lung cancer starting from an appropriate in vivo pre-clinical model." (PMID 33987090, 2021). "Therefore, we unveil that DHX36 presents clinical significance and plays a role in tumour suppression in lung cancer, and propose a potentially new concept for an anti-cancer therapy based on helicase-specific targeting." (PMID 33987090, 2021). "We demonstrate that the knockdown of DHX36 enhances the migration capacity of lung cancer cells." (PMID 33987090, 2021). "Furthermore, the reduction of DHX36 level de-sensitises the proliferation response of lung cancer cells to chemotherapeutic drugs such as paclitaxel, with cell dependence." (PMID 33987090, 2021). "However, the role of the dominant G4 resolvase DHX36 in the progression of lung cancer remains unknown." (PMID 33987090, 2021). "DHX36 functions through regulating multiple signalling pathways including activation of protein activity, protein autophosphorylation, Fc-receptor signalling pathway, response to peptide hormone and stress-activated protein kinase signalling cascade in lung cancer cells." (PMID 33987090, 2021). "Future studies should be encouraged to pin-point the actual cellular and molecular mechanisms of DHX36 function in lung cancer by either activation or overexpression of DHX36, which could be proceeded by either CRISPR-based genomic editing or small molecules predicted by chemical docking simulation." (PMID 33987090, 2021). "Whilst there is no previous report of DHX36 function in lung cancer, there is indirect evidence with DHX9, a DHX36 paralog among the DEAH-box helicases." (PMID 33987090, 2021).
male infertility (1 paper, 2025). The inability of the male to effect fertilization of an ovum after a specified period of unprotected intercourse. "DHX36 is most abundant in the testes, and deficiency of DHX36 in spermatogonia leads to male infertility, suggesting that it has important functions in germ cells." (PMID 40304181, 2025).
myocardial infarction (1 paper, 2026). Gross necrosis of the myocardium, as a result of interruption of the blood supply to the area, as in coronary thrombosis. "Future studies incorporating additional models, such as myocardial infarction or ischemia–reperfusion models, would provide complementary insights into the broader spectrum of CHD pathology and further validate the roles of DHX36 and GPR68 across different disease contexts." (PMID 41614904, 2026).
Obesity (1 paper, 2020). Accumulation of substantial excess body fat. "In the case of pre-miR-26a-1, G4 unwinding achieved by the RNA helicase DHX36 favors the physiological accumulation of mature miR-26a, and impairing DHX36 activity leads to low miR-26a abundance and obesity." (PMID 32545267, 2020).